TIMP4 (TIMP metallopeptidase inhibitor 4)
Diseases named in the same sentence as TIMP4 in open-access papers (continued):
Sharing a sentence is not in itself a finding about the gene and the disease.
glioblastoma (6 papers, 2013 to 2025). The most malignant astrocytic tumor (WHO grade IV). "In contrast, an increased expression of TIMP4 was associated with good prognosis of glioblastoma (HR 0.88, 95% CI 0.79–0.98, p = 0.025)." (PMID 31653034, 2019). "Further, CD63 was found to interact with TIMP-4, and CD63/TIMP-4 co-expression was associated with poorer outcome in glioblastoma patients." (PMID 29523123, 2018). "Conversely, the upregulation of the TIMP4 gene was typical for malignant forms, including glioblastomas and astrocytomas with grades III to IV." (PMID 38474106, 2024). "In meningiomas, the mRNA level of TIMP4 was decreased compared to the glioblastoma (p < 0.001) and astrocytoma (p < 0.001) groups." (PMID 38474106, 2024). "Although the MMP9 gene alone is considered a prognostic marker for glioblastomas, we are the only ones to point to the role of the malignancy grade in relation to TIMP4." (PMID 38474106, 2024). "In human glioblastoma multiforme, SYN2 and TIMP4, a metalloproteinase-encoding gene located within an intron of SYN2, are subjects to reciprocal deregulation." (PMID 24886479, 2014). "We found eight deregulated genes in the glioblastoma group compared to the benign meningioma group, with only MMP9 (FC = 2.55; p = 0.09) and TIMP4 (7.28; p < 0.0001) upregulated in an aggressive form." (PMID 38474106, 2024). "Altogether, these results suggest that TIMP-1 is a stronger prognosticator in glioblastoma patients compared to CD63 and TIMP-4." (PMID 29523123, 2018).
Hypertension (6 papers, 2013 to 2025). The presence of chronic increased pressure in the systemic arterial system. "Our subgroup analysis was carried out to see if independent CVD risk factors such as age, BMI and a history of hypertension exerted significant influence on the extent of change in the levels of MMP-8, MMP-9 and TIMP-4 during the 5-year follow-up period." (PMID 32451401, 2020). "We suggest that the increased production of MMPs, due to the mechanical stress induced by hypertension, should be accompanied by an increased expression of TIMP-4." (PMID 31781384, 2019). "Patients diagnosed with hypertension had increased levels of periostin (p < 0.05) and TIMP-4 (p < 0.01) when compared to non-hypertensive patients." (PMID 34135421, 2021). "An additional risk factor such as hypertension did not cause significant changes in the levels of MMP-2, MMP-9, and TIMP-4." (PMID 31781384, 2019).
prostate carcinoma (6 papers, 2005 to 2025). A carcinoma that arises from epithelial cells of the prostate gland. "A high-expression of TIMP4 has been found in patients with breast, cervical, and prostate cancers, whereas a low expression has been observed in patients with pancreatic cancer." (PMID 31130992, 2019). "The expression of TIMP4 was revealed to be a protective factor for prostate cancer progression." (PMID 22200787, 2012). "MMP-26 and TIMP-4 may play an important role in the transformation of high-grade prostatic intraepithelial neoplasia (HGPIN) to invasive carcinoma and may potentially act as diagnostic indicators for early prostate cancer." (PMID 37255653, 2022). "In cancer, MMP-26 expression is upregulated in human breast ductal carcinoma in situ, related to invasion 45, and in prostate cancer peaking of MMP-26 and TIMP-4 marks the invasive transition." (PMID 23634280, 2013).
atherosclerosis (5 papers, 2020 to 2025). A disease characterized by the build-up of fatty material and calcium deposition in the arterial wall resulting in partial or complete occlusion of the arterial lumen. "TIMP4 has been shown to accumulate locally within arterial walls during inflammatory processes as a response to atherosclerosis and giant cell arteritis." (PMID 38915119, 2024). "Among them, TIMP4 was selected for the further research, because its close relationship with CAS and atherosclerosis as previously reported." (PMID 37328892, 2023). "The presence of atherosclerosis (p = 0.7) did not have an effect on TIMP4 score in CAA patients." (PMID 38915119, 2024).
atrial fibrillation (5 papers, 2015 to 2025). A disorder characterized by an electrocardiographic finding of a supraventricular arrhythmia characterized by the replacement of consistent P waves by rapid oscillations or fibrillatory waves that vary in size, shape and timing and are accompanied by an irregular ventricular response. "TIMP-4 was also negatively correlated with atrial fibrosis and ECM changes in the atria of rheumatic heart disease with atrial fibrillation." (PMID 39992996, 2025). "As a result of TaqMan qPCR and Western analysis, the relative mRNA and protein expression level of three target genes (DIER-1, TIMP-4 and CACNA1C) were significantly lower in the atrial fibrillation group than that in the healthy control group." (PMID 26319023, 2015). "Although there are no studies associating TIMP4 with GDF-15; this extracellular matrix protein has been associated with atrial fibrillation, which could help understand the relationship between GDF-15 and this arrhythmia." (PMID 34441356, 2021). "Atrial fibrillation patients with severe aortic stenosis present increased atrial fibrosis and collagen type III synthesis, with extracellular matrix remodelling demonstrated by a decrease in the MMP16/TIMP4 ratio, along with an increased serum TIMP1 and TIMP2 proteins." (PMID 33129260, 2020).
cervical cancer (5 papers, 2015 to 2023). A primary or metastatic malignant neoplasm involving the cervix. "However, relatively recent studies suggest that overexpression of TIMP-4 might cause more rapid cervical cancer growth in mice." (PMID 35655767, 2022). "In cervical cancer, TIMP4 was newly expressed and found to correlate with the advanced clinical stage." (PMID 36982551, 2023). "The upregulation of TIMP4 gene prevents the metastasis of human cervical cancer cells by inhibiting PI3K/Akt/snail signaling pathway and blocking epithelial-mesenchymal transition (EMT)." (PMID 35847900, 2022). "Recently, it has been shown that in nude mice, cervical cancer cells that overexpress TIMP-4 form tumours faster than the controls, thus providing evidence for a TIMP-4 related regulation of stemness." (PMID 36013323, 2022). "We observed the striking ability of TIMP-4 to enhance apoptosis in cervical cancer cell lines after death receptor ligand (TNF-α and TRAIL) treatment and serum starvation." (PMID 26291714, 2015). "Our previous report demonstrated that, in cervical cancer patients, TIMP-4 expression increases in more advanced clinical stages." (PMID 26291714, 2015). "Similar to previous results, in the present research we showed that TIMP-4 sensitizes cervical cancer cells to death in vitro." (PMID 26291714, 2015). "In the present report, we observed that TIMP-4 up-regulation sensitizes cervical cancer cells to apoptosis through the modulation of apoptotic proteins from the IAPs, FLIP and Bcl-2 families." (PMID 26291714, 2015). "Our previous work showed that TIMP-4 is expressed de novo in cervical cancer with increased levels in more advanced stages." (PMID 26291714, 2015). "In conclusion, the current work demonstrates that TIMP-4 exhibits an anti-tumorigenic apoptosis-sensitizing role in cervical cancer cells." (PMID 26291714, 2015). "TIMP-4 is expressed de novo in cervical cancer cells and increases in advanced clinical stages." (PMID 36982551, 2023). "To analyze whether TIMP-4 also regulates cell death in cervical cancer cells, we generated a HeLa cell line that stably overexpresses TIMP-4 (hereafter named H-TIMP-4) and control cell line (hereafter called H-Vector)." (PMID 26291714, 2015).
liposarcoma (5 papers, 2019 to 2025). A usually painless malignant tumor that arises from adipose tissue. "Stable TIMP-4 knockdown promotes the proliferation and migration of well-differentiated liposarcoma (WDLS)." (PMID 34781885, 2021). "TIMP4 expression in turn is relatively high in well-differentiated liposarcoma and low in the more aggressive undifferentiated liposarcoma, whereas TIMP1 shows an opposite expression pattern in these sarcomas." (PMID 31466240, 2019). "Recent genetic studies have identified distinct molecular profiles in liposarcomas: well‐differentiated liposarcomas exhibit high levels of TIMP‐4 and low YAP/TAZ expression, whereas dedifferentiated liposarcomas show elevated TIMP‐1 and activated YAP/TAZ levels." (PMID 39872705, 2025). "In patients with dedifferentiated liposarcoma (DDLS), the conversion of Tissue Inhibitors Of Metalloproteinase 4 (TIMP-4) to TIMP-1 is associated with poor prognosis.TIMP-1 knockout, TIMP-4 overexpressing, or VP-mediated YAP/TAZ blockade can inhibit the proliferation and migration of DDLS cells." (PMID 33178014, 2020). "Gene expression of TIMP4 is low in sarcomas except for liposarcoma." (PMID 31466240, 2019).
Myocardial fibrosis (5 papers, 2008 to 2023). "On the other hand, micehyperexpressing the profibrotic cytokine TGF-beta develop myocardial fibrosis andhave a 2.5 increase of TIMP-4 myocardial expression compared to nontransgenic controlmice." (PMID 19190762, 2008). "Interestingly, TIMP4 was found not to contribute to cardiac response to mechanical stress, as TIMP4−/− mice exhibited comparable cardiac remodeling, dysfunction and myocardial fibrosis compared with the parallel wildtype mice." (PMID 22943504, 2012).
ovarian carcinoma (5 papers, 2013 to 2022). A malignant neoplasm originating from the surface ovarian epithelium. "Chegini’s Lab has reported elevated expression of TIMP-4 in ovarian cancer tissues by IHC analysis, indicating its potential role in tumorigenesis of ovarian cancer." (PMID 24116163, 2013). "The analysis showed a panel of five serum protein markers (MSP-alpha, TIMP-4, PDGF-R alpha, OPG, and CA125) that might effectively detect ovarian cancer with high specificity (95%) and high sensitivity (100%), with AUC = 0.98, while CA125 had AUC = 0.87." (PMID 32143328, 2020). "A panel of 5 serum protein markers (MSP-alpha, TIMP-4, PDGF-R alpha, and OPG and CA125) was identified, which could effectively detect ovarian cancer with high specificity (95%) and high sensitivity (100%), with AUC =0.98, while CA125 alone had an AUC of 0.87." (PMID 24116163, 2013).
Alzheimer disease (4 papers, 2022 to 2024). A progressive, neurodegenerative disease characterized by loss of function and death of nerve cells in several areas of the brain leading to loss of cognitive function such as memory and language. "Since 80% of AD patients also have CAA, and TIMP4 has been particularly associated with cardiovascular processes, one may speculate that TIMP4 is linked to Alzheimer’s dementia through disturbed vascular integrity associated with CAA." (PMID 38915119, 2024). "Increased levels of TIMP4 have been measured in plasma of Alzheimer’s dementia patients, even in early stages of disease." (PMID 38915119, 2024).
cholesteatoma (4 papers, 2021 to 2024). A pathologic process characterized by the proliferation of keratinizing squamous epithelium resulting in the accumulation of keratin and cells in the middle ear and/or mastoid. "These assumptions about TIMP-4 being a stimulant of tumorigenic activity, based on our results, lead us to believe that TIMP-4 is likely associated with the aggressiveness of cholesteatoma." (PMID 35655767, 2022). "Correlation between MMP-9 and TIMP-4 suggests that TIMP-4 in cholesteatoma tissue intercorrelates to MMP-9." (PMID 35655767, 2022). "A very strong correlation between MMP-9 and TIMP-4 suggests that TIMP-4 in cholesteatoma tissue intercorrelates to MMP-9." (PMID 35655767, 2022). "The main goal of our study was to describe the transcription factor (NF-κβ), angiogenetic factor (VEGF), and remodeling markers (MMP-9 and TIMP-4) of the cholesteatoma tissue compared to control skin tissue." (PMID 35655767, 2022). "A statistically significant higher numbers of NF-κβ and TIMP-4 immunoreactive cells in the cholesteatoma compared to control group." (PMID 35655767, 2022). "It suggests that TIMP-4 is interconnected to MMP-9 in cholesteatoma." (PMID 35655767, 2022). "As we proved intercorrelation between MMP-9 and TIMP-4 in cholesteatoma, we suggest that these remodeling factors might also influence bone remodulation in middle ear bone." (PMID 35655767, 2022). "Additionally, we found that TIMP-4 in the cholesteatoma matrix has a very strong positive correlation with MMP-9 and a moderate correlation between TIMP-4 in matrix and MMP-9 in perimatrix." (PMID 35655767, 2022). "However, we showed a statistically significant difference between TIMP-4 in cholesteatoma perimatrix and controlled connective tissue." (PMID 35655767, 2022). "Our data shows that TIMP-4 is overexpressed in cholesteatoma." (PMID 35655767, 2022). "Therefore, the aim of our work was to describe the distribution of transcription factor (NF-κβ), angiogenetic factor (VEGF), and remodeling markers (MMP-9 and TIMP-4) of the cholesteatoma." (PMID 35655767, 2022). "Additionally, TIMP-4 was significantly more expressed in cholesteatoma tissue than TIMP-2." (PMID 38535082, 2024). "Thus, we suggest that TIMP-4 is relevant in the activity of cholesteatoma in the middle ear." (PMID 35655767, 2022). "A statistically significant difference between TIMP-4 in perimatrix and skin connective tissue indicates that TIMP-4 likely regulates the development of cholesteatoma." (PMID 35655767, 2022). "Additionally, to our knowledge, several tissue factors such as SHH, HβD-4, and TIMP-4 have not been analyzed in cholesteatoma tissue." (PMID 38535082, 2024). "A literature review does not show articles regarding TIMP-4 relations with cholesteatoma." (PMID 35655767, 2022). "Still, there are no data available on how TIMP-4 acts in cholesteatoma tissue." (PMID 34682191, 2021). "Therefore, there are no scientific studies and information related to TIMP-4 and cholesteatoma." (PMID 35655767, 2022).
psoriasis (4 papers, 2019 to 2025). An autoimmune condition characterized by red, well-delineated plaques with silvery scales that are usually on the extensor surfaces and scalp. "We found that MMP2, MMP12, MMP13, TIMP2, and TIMP4 distinguished psoriasis from psoriatic arthritis patients undergoing a systemic treatment, with a good diagnostic accuracy (Area under the ROC Curve (AUC) > 0.7)." (PMID 31717649, 2019). "A set of biomarkers, composed matrix metalloproteinases, and their tissue inhibitors comprises MMP2, MMP12, MMP13, TIMP2, and TIMP4 whose circulating levels are higher psoriasis undergoing systemic therapy compared to the parallel with psoriatic arthritis cohort." (PMID 34715781, 2021). "By intersecting the differential genes identified in all four datasets, we identified 15 common genes that exhibited high expression in both BC and psoriasis, with the exception of INA, WIF1, and TIMP4." (PMID 38605947, 2024).
pulmonary hypertension (4 papers, 2008 to 2022). Increased pressure within the pulmonary circulation due to lung or heart disorder. "Individual PASP measurements suggestive of pulmonary hypertension were associated with increased TIMP-4 serum levels (P = .03), independently of age, extent of skin sclerosis, or lung fibrosis, suggesting a cardiopulmonary vasculature-specific role of TIMP-4 activation in SSc." (PMID 19190762, 2008). "Moreover, studies in individuals with pulmonary hypertension have indicated that TIMP4 levels correlate with hemodynamic parameters." (PMID 32171287, 2020). "It is unknown whether the association we observed between DLCO or CPI and peripheral blood TIMP4 expression reflects pulmonary vascular remodeling and development of pulmonary hypertension, accumulating lung fibrosis, or the effects of angiogenesis supporting pulmonary hypertension and fibroplasia." (PMID 32171287, 2020). "The MMP2/TIMP4 ratio was detected as a marker of myocardial dysfunction and as a negative predictor for survival in idiopathic pulmonary hypertension." (PMID 36293543, 2022).
Arthritis (3 papers, 2005 to 2013). Inflammation of a joint. "Systemic transduction with TIMP-4 was reported to reduce both adjuvant-induced arthritis and periodontitis in rats." (PMID 23577057, 2013). "In a recent study of adjuvant induced arthritis in a rat model, arthritic changes were associated with raised levels of MMPs, IL-1β and TNF-α in joint tissue; this was ameliorated after TIMP-4 gene therapy in the treated group compared with the untreated control animals." (PMID 19088876, 2008).
astrocytomas (3 papers, 2015 to 2024). "We examined the mRNA expression profiles of RECK transcripts, as well as of MMPs reportedly inhibited by canonical RECK (MMP-2, -9 and -14), and of endogenous tissue inhibitors of MMPs (TIMP-1, TIMP-2, TIMP-3 and TIMP-4) in astrocytomas of different grades of malignancy." (PMID 26431549, 2015). "Among the tissue inhibitors of metalloproteinases, we determined a statistically significant downregulation of the gene TIMP4 (−11.2) in meningiomas and TIMP2 (−2.0) in astrocytomas." (PMID 38474106, 2024). "Similar results were obtained in astrocytomas: specifically, in the genes MMP3, MMP8, MMP10, TIMP2, and TIMP4." (PMID 38474106, 2024).
dyslipidemia (3 papers, 2017 to 2022). "TIMP4 KO mice showed reduced cardiac fibrosis and systemic protection from dyslipidemia, indicating a protective mechanism in the context of metabolic changes." (PMID 32937927, 2020). "Timp4−/–-HFD mice were also protected from HFD-induced liver and skeletal muscle triglyceride accumulation and dyslipidemia." (PMID 28740132, 2017). "Timp4−/− mice fed HFD exhibit defective lipid absorption leading to reduced adipocyte hypertrophy, fibrosis, and diminished hepatic steatosis and dyslipidemia." (PMID 28740132, 2017).
Hepatic fibrosis (3 papers, 2013 to 2023). The presence of excessive fibrous connective tissue in the liver. "TIMP-4 mRNA has been shown to be increased in a model of experimental biliary atresia, but apart from that data on the role of TIMP-4 for liver disease and hepatic fibrosis are scarce." (PMID 23516586, 2013). "Taken together, these results suggest that increased expression of TIMP-4 and Endoglin represents a mechanism specific for hepatic fibrosis that correlates with hepatic staging but is irrespective of the underlying etiology of liver disease." (PMID 23516586, 2013).
ischaemic stroke (3 papers, 2022 to 2024). "In 225 patients with ischaemic stroke, signs of cSVD (i.e. white matter changes, lacunes, and brain atrophy) were associated with higher circulating TIMP4 levels." (PMID 38915119, 2024).
lung fibrosis (3 papers, 2008 to 2020). "In the presentstudy, we found that TIMP-4 serum levels are increased in patients with eitherdiffuse or limited SSc as well as in patients with pulmonary fibrosis." (PMID 19190762, 2008). "Also, TIMP-4 levels were significantly higherin patients with pulmonary fibrosis (2157 ± 1068 ng/mL, range 846–4900 ng/mL) thancontrols." (PMID 19190762, 2008). "However, in the subgroup of patients with PASP measurements lower to 40 mmHg (n = 69), TIMP-4 levels were comparable to controls irrespective of the presence of diffuse or limited skin involvement, or lung fibrosis." (PMID 19190762, 2008).
preeclampsia (3 papers, 2017 to 2024). Preeclampsia is a hypertensive disorder of pregnancy that is characterized by new-onset hypertension with proteinuria presenting after 20 weeks of gestation, and depending on mild or severe forms may initially present with severe headache, visual disturbances, and hyperreflexia. "TIMP4, serving as a tissue metalloproteinase inhibitor, can inhibit trophoblastic invasion and migration in the presence of long non-coding RNA, which is associated with the pathogenesis of preeclampsia." (PMID 39273344, 2024). "Additionally, reduced GCM1 expression has been linked with increased tissue inhibitor of metalloproteinase-4 (TIMP4) expression in preeclampsia, indicating a mechanistic link between GCM1, placental tissue-remodeling and placental vascularization." (PMID 28383551, 2017).